TAGLN2 (transgelin 2)
Diseases named in the same sentence as TAGLN2 in open-access papers (continued):
Sharing a sentence is not in itself a finding about the gene and the disease.
tumor (continued). "Moreover, there was a close positive correlation between the expression of TAGLN2 and YBX1 in DAPI+ cells of both tumor and paracancerous tissues (r = 0.1657, P = 0.027)." (PMID 39168971, 2024). "Furthermore, the correlation became more significant when focusing on the cells with TAGLN2- and YBX1-positive signals (TAGLN2+YBX1+) in all tumor and paired control tissues (r = 0.6820, P < 0.0001) and only tumor tissues (r = 0.6882, P < 0.0001)." (PMID 39168971, 2024). "Moreover, a high degree of correlation between TAGLN2 and MHC genes was observed in most tumor types." (PMID 37476180, 2023). "The proteomic analysis of tumor tissues identified that rho-associated coiled-coil containing protein kinase 1 (ROCK1), transgelin 2 (TAGLN2), and FCH and Mu domain containing endocytic adaptor 2 (FCHO2) levels were significantly reduced in chrysin-treated tumor tissues." (PMID 36077069, 2022). "Statistical analysis of clinical data for patients with GC revealed that sex, age, histological grade, tumor size, T stage and overall cancer stage (Stage I-IV) were not significantly correlated with the Tagln2 expression in ECs." (PMID 34150622, 2021). "Transgelin-2 expression is up-regulated in several cancers with its staining being higher in tumor cells rather than in tumor stroma." (PMID 35011306, 2021). "Interestingly, however, we observed that whole-body transgelin-2-KO (Tagln2−/−) mice, as compared to wild-type (WT) mice, developed rapid B16F10-derived tumor growth, resulting in increased tumor weights and sizes." (PMID 33731208, 2021). "Similar to the GM-CSF-induced BMDCs, Tagln2−/− cDC1s were not able to optimally control tumor growth in mice, suggesting that transgelin-2 is also important for the function of cDC1s to facilitate optimal antigen presentation." (PMID 33731208, 2021). "However, because tumor microenvironments are typically immunosuppressive due to the dominant populations of malignant cells, stroma, and regulatory T cells, immunologically suppressed effector cells in the tumor microenvironment may express low levels of transgelin-2." (PMID 33898417, 2021). "The function of Tagln2 in tumor progression has not yet been clarified; importantly, the precise biological role and underlying mechanism of this molecule in tumor angiogenesis has rarely been reported." (PMID 34150622, 2021). "Similarly, the elevated expression of TAGLN2 was observed in uterine cervical squamous cell carcinoma (SCC), while suppression of TAGLN2 in human uterine SCC cells significantly inhibited tumor growth and invasion." (PMID 29110682, 2017). "Our past miRNA studies of BC cells showed that clustered miRNAs (including miR-1/133a (targeting TAGLN2), miR-23b/27b/24-1 (targeting EGFR, MET, and FOXM1), and miR-195/497 (targeting BIRC5 and WNT7A)) act as tumor-suppressive miRNAs through their regulation of several oncogenic genes and pathways." (PMID 27072587, 2016). "A recent study suggested that TAGLN2 has a negative influence on metastasis suppressing the invasive capacity of tumor cells." (PMID 23504277, 2013). "Their role in tumor metastasis requires further investigation, but the role may be similar to that of proteins such as TPI-1, ENO1, and TAGLN2." (PMID 23504277, 2013). "Moreover, elevated expression of Tagln2 in tumor-derived ECs but not in the whole mixed tumor tissue was reported for the first time." (PMID 34150622, 2021). "In accordance with the metastatic model, Tagln2−/− BMDCs could not optimally control tumor growth in mice." (PMID 33731208, 2021). "Thus, we next tested whether TAGLN2 enables the use of these fatty acids to sustain mitochondrial activity in activated CD8+ T cells experiencing glucose restriction, which is a prevalent condition in the tumor milieu." (PMID 38168227, 2023).
tumor (continued). "The analysis revealed that TAGLN2 expression in normal breast, stomach, skin, kidney, cervix, colon, endometrium, nasopharynx, liver, lung, ovary, pancreas, and urinary bladder tissues were weak or negative, whereas in the corresponding tumor tissues, such expressions were moderate or strong." (PMID 37476180, 2023). "Our data revealed that TAGLN2 knockdown or CRNN overexpression inhibited ESCC PDX tumor growth, leading to reduced tumor volume and tumor weight, without any adverse effects on the mice body weight." (PMID 37553345, 2023). "In accordance with the previous results, overexpression of transgelin-2 (TG2) in OTI T cells did not enhance T cell adhesion to ovalbumin (OVA)-pulsed B16F10 target cells in vitro and showed only a mild effect on B16F10 tumor regression in vivo." (PMID 33731208, 2021).
cancer (60 papers, 2007 to 2026). A tumor composed of atypical neoplastic, often pleomorphic cells that invade other tissues. "TAGLN2 overexpression is also associated with the malignant transformation of cancer, such as resistance, metastasis, and invasion contributing as a candidate biomarker for diagnosis, treatment, and prognosis of cancer." (PMID 38918474, 2024). "Distant metastases (M), T stage, and overall cancer stage (Stage I~IV) exhibited a significant association with TAGLN2 expression in the cytoplasm." (PMID 39168971, 2024). "And correlation analysis of CNVs levels of TAGLN2 and TAGLN2 expression levels showed a significant association between the two in 26 cancers." (PMID 37476180, 2023). "Our research, however, focuses on a distinct yet significant epigenetic modification - methylation - and presents compelling evidence that methylation of TAGLN2 is closely associated with the prognosis of certain types of cancer." (PMID 37476180, 2023). "Studies have demonstrated that the expression of Transgelin-2 is positively associated with worse prognosis of different cancers." (PMID 36204303, 2022). "Although the topic is still debated, transgelin-2 has been implicated in tumorigenesis and cancer development." (PMID 33731208, 2021). "Several studies have demonstrated that transgelin-2 expression in cancer cells is also associated with increased drug resistance." (PMID 33898417, 2021). "Together, these data suggest that the upregulation of transgelin-2 is associated with tumorigenesis and cancer development." (PMID 33898417, 2021). "Upregulation of transgelin-2 expression is associated with metastasis and invasion of various cancer cells, including lung, bladder, colorectal, esophageal, and gastric cancers." (PMID 33898417, 2021). "TAGLN2 is also overexpressed in various cancers, and its dysregulation is associated with the progression of malignant tumors." (PMID 34530821, 2021). "Although transgelin-2 is known to be involved in the development of cancer, the relationship between transgelin-2 and driver gene mutation is not fully understood." (PMID 30041673, 2018). "Several drugs including statins, Salvianolic acid A, Paeonol and SB-T-121205 regulate cancer cell metastasis and are associated with transgelin-2 expression." (PMID 30041673, 2018). "Next, we analyzed the dataset of the Cancer Cell Family Encyclopedia (CCLE) to further investigate the relationship between expression of transgelin-2 and KRAS mutation in PDAC cells." (PMID 30041673, 2018). "Several studies have demonstrated that the level of transgelin-2 is associated with prognosis in various cancers." (PMID 28521289, 2017). "The underlying mechanisms of transgelin-2 in cancer behavior is involved in interacting with specific proteins." (PMID 28521289, 2017). "In other cases, transgelin-2 influences signaling pathways through association with cancer-related proteins." (PMID 28521289, 2017). "Gene set enrichment analysis (GSEA) Hallmark pathway analysis using a STAD dataset from TCGA revealed that TAGLN2 is involved in many signaling pathways associated with cancer, including apoptosis, hypoxia, MYC targets, KRAS signaling, and the reactive oxygen species pathway." (PMID 39168971, 2024). "However, recent reports have demonstrated that TAGLN2 is associated with cancer progression, migration, invasion and prognosis." (PMID 39168971, 2024). "Besides, we noticed that TAGLN2 was closely linked to cell cycle or mitosis regulation in some certain cancer types." (PMID 37476180, 2023). "Notably, we also proved a positive correlation between cancer-associated fibroblasts and TAGLN2 expression in most cancer types, excluding THYM and UCEC." (PMID 37476180, 2023). "TAGLN2 is a gene that has been suggested to be associated with cancer development, and suppressing this gene is considered to inhibit the growth, invasion, and metastasis of cancer cell." (PMID 36376423, 2022).
cancer (continued). "As described in previous reports, Tagln2 is essential for the formation of stable immunological synapses between cytotoxic T cells and cancer cells, and Tagln2-actin-lymphocyte function-associated antigen-1 (LFA-1) axis for the effects of adoptive T cell therapy." (PMID 34150622, 2021). "In the future, new strategies or methods that selectively control the expression or suppression of transgelin-2 in immune cells and cancer cells may help treat transgelin-2-associated cancers." (PMID 33898417, 2021). "Several studies have demonstrated that TAGLN2 expression in cancer cells is associated with increased drug resistance, and selectively suppressed TAGLN2 expression may prevent multidrug resistance in cancer chemotherapy." (PMID 34771544, 2021). "Moreover, highly expressed TAGLN2 was associated with reduced PFI in these cancers." (PMID 37476180, 2023). "Current evidence reveals stark divergence in miR-145s targets across urologic tumors (e.g., SOX11 vs. TAGLN2), underscoring the need for cross-cancer studies to distinguish conserved from context-dependent mechanisms." (PMID 40689207, 2025). "TAGLN2, initially identified as a cytoskeletal protein involved in the stabilization of actin stress fibers, has emerged as a multifunctional regulator in cancer biology, contributing to various processes that drive tumorigenesis and disease progression." (PMID 41169389, 2025). "TAGLN2 is aberrantly expressed in various cancers, including gastric and esophageal cancers, with high expression correlating with increased malignancy and metastatic potential." (PMID 39981244, 2025). "TAGLN2 was highly expressed in BTC tissues, especially in cancer-associated fibroblasts in the stroma." (PMID 38509504, 2024). "The findings of the present study demonstrated that TAGLN2 expression in patient tissues was increased in stromal tissues around cancer cells and that stromal expression of TAGLN2 was related to patient prognosis." (PMID 38509504, 2024). "Recently, TAGLN2 has emerged as a biomarker that plays an essential role in developing various types of cancer." (PMID 38509504, 2024). "In the patient tissues, TAGLN2 is expressed in cancer cells with an overall high expression intensity, making it challenging to analyze its correlation with prognosis." (PMID 38509504, 2024). "Studies have identified TAGLN2 among other prognostic hub genes as predictors of prognosis in certain cancer types, indicating a potential relationship between TAGLN2 and IFN-induced genes." (PMID 39168971, 2024). "In the stroma of cancer tissues, TAGLN2 was overexpressed, and its localization coincided with α-SMA expression." (PMID 38509504, 2024). "Subsequently, TAGLN2 expression in 41 surgical samples of human BTC using IHC in cancer cells and stroma around cancer was evaluated." (PMID 38509504, 2024). "Targeting TAGLN2 is expected to be a successful anti-cancer therapy for advanced cancer following chemotherapy failure." (PMID 38509504, 2024). "Our analysis revealed that TAGLN2 was expressed in both types of epithelial cells and exhibited higher expression levels in cancer tissue compared to the normal group." (PMID 37553345, 2023). "Initially, we tested TAGLN2 distribution in cancer cells, and in line with our results, we unraveled that TAGLN2 was indeed abundant in the cytoplasm." (PMID 37476180, 2023). "In our study, utilizing bioinformatics methods, we carried out an in-depth pan-cancer analysis on TAGLN2, comprising of expression level, prognostic traits, alteration, DNA methylation, and functional enrichment analysis." (PMID 37476180, 2023). "Later on, we evaluated the prognostic traits of TAGLN2 in 33 types of cancers which was a meaningful study to facilitate the translation of basic science to clinical studies." (PMID 37476180, 2023). "Cancer cells had approximately two-fold increase in TAGLN2 expression compared with corresponding normal tissues." (PMID 37476180, 2023).
cancer (continued). "We amplified that TAGLN2 was positively correlated with most cancer-promoting pathways, such as glycolysis, apoptosis, hypoxia, EMT, PI3K AKT MTOR signaling, and angiogenesis." (PMID 37476180, 2023). "To this, these results suggested that TAGLN2 seemed to be capable of guiding the treatment of cancer to a certain degree." (PMID 37476180, 2023). "Of note, we provide several unique perspectives on the potential use of TAGLN2 as a therapeutic target for cancer treatment." (PMID 37476180, 2023). "By analyzing the available data, we investigated the prognostic significance of TAGLN2 in pan-cancer." (PMID 37476180, 2023). "Of note, although TAGLN2 expression has been clarified in several cancers hitherto, its related research about TAGLN2 gene alteration in human cancers should be deeply explored in the future." (PMID 37476180, 2023). "We discovered that genetic changes of TAGLN2 were mostly of the “amplification” type, which were significantly observed in almost all TCGA cancer cases." (PMID 37476180, 2023). "According to the aforestated analysis results, we recognized the potential role of TAGLN2 in pan-cancer, especially in UCEC." (PMID 37476180, 2023). "Aiming to investigate the correlation between immune cell infiltration and TAGLN2 expression at the pan-cancer level, we explored various publicly available data repositories to analyze the relationship between these two variables." (PMID 37476180, 2023). "The present study found that TAGLN2 had a remarkable correlation with TMB in 8 cancers and MSI in 8 cancers." (PMID 37476180, 2023). "The present research findings demonstrated that TAGLN2 expression in 33 malignancies had a positive correlation with TME involving antigen processing machinery, DNA damage, and repair; the latter two of these accounted for the majority." (PMID 37476180, 2023). "Collectively, we preliminarily illustrated the oncogenic role and prognostic value of TAGLN2 in pan-cancer." (PMID 37476180, 2023). "We first monitored in detail the expression levels of TAGLN2 mRNA and protein in human organs, tissues, and cell lines and compared them with those found in various cancers." (PMID 37476180, 2023). "Initially, we displayed the genetic alteration landscape of TAGLN2 across all cancer types in the TCGA cohort, depicting that the most frequent alteration was amplification." (PMID 37476180, 2023). "In terms of OS, TAGLN2 was a hazard factor in several cancers, including LGG, UVM, LAML, LIHC, MESO, KICH, and ACC, and was correlated with shorter survival times." (PMID 37476180, 2023). "Of note, as a protein affecting dynamics of the actin cytoskeleton via stabilization of actin filaments, TAGLN2 is also both directly and indirectly involved in many cancer-related processes such as migration, proliferation, differentiation, or apoptosis." (PMID 37476180, 2023). "Here, LCP1, PRDX2, OGN and, TAGLN2 together with other molecular interactors, linked with highest hits, according to KEGG database, to pathways in cancer, PI3K-AKT and MAPK signaling pathways." (PMID 38322285, 2023). "Our findings revealed that TAGLN2 was extensively upregulated in 23 cancers, while presenting lower expression in KICH, LAML, PRAD, and THYM as compared to adjacent and normal tissues." (PMID 37476180, 2023). "All these findings highlight that TAGLN2 is widely expressed and engaged in the development of cancers." (PMID 35505656, 2022). "A recent study demonstrated that transgelin-2 is an essential protein for cancer and immunity and can act as a double-edged sword for cancer therapy." (PMID 35074008, 2022). "Our findings indicate that cell-permeable transgelin-2 have a potential clinical value as a cancer immunotherapy based on DCs." (PMID 33731208, 2021). "In some cancer cells, transgelin-2 is known to inhibit cellular motility by suppressing actin polymerization." (PMID 33731208, 2021).